RNU2-25P (RNA, U2 small nuclear 25, pseudogene)
Gene: Small nuclear RNA gene on chromosome 9 (2,162,763 to 2,162,953, reverse strand). Ensembl gene ENSG00000222973.
Homologues: Orthologues: chimpanzee U2 (98% identical), macaque U2 (97% identical), pig U2 (68% identical). Paralogues in human: U2 (87% identical), U2 (84% identical), RNU2-2 (83% identical), RNU2-3P (83% identical), RNU2-48P (83% identical), RNU2-4P (82% identical), RNU2-52P (81% identical), RNU2-17P (81% identical), RNU2-26P (81% identical), RNU2-57P (81% identical), RNU2-32P (78% identical), RNU2-43P (78% identical), and 66 more.